IL1A (interleukin 1 alpha)
Diseases named in the same sentence as IL1A in open-access papers (continued):
Sharing a sentence is not in itself a finding about the gene and the disease.
skin infection (4 papers, 2011 to 2024). An inflammatory process affecting the skin, caused by bacteria, viruses, parasites, or fungi. "In a Staphylococcus aureus skin infection model, IL-17A/F−/− mice had reduced IL-1α, IL-1β, and TNF-α,39 suggesting that IL-17 regulates these proinflammatory mediators." (PMID 39504049, 2024). "Thus, although IL-1β-producing neutrophils are sufficient for neutrophil recruitment during a S. aureus skin infection, neutrophil recruitment during sterile inflammation is mediated by IL-1α, IL-1β or both IL-1α and IL-1β, depending on the anatomical site and the type of inflammation." (PMID 23209417, 2012). "Proinflammatory cytokines and chemokines, such as IL-1α, IL-6, TNFα, and CXCL8, secreted by various cell types play a fundamental role in attracting neutrophils and T cells to the place of skin infection." (PMID 21619700, 2011). "IL-17A, IL-1α, and IL-1β are believed to be protective during mouse MRSA skin infections." (PMID 33573328, 2021).
staphylococcus aureus infection (4 papers, 2020 to 2025). An infectious process in which the bacteria Staphylococcus aureus is present. "Furthermore, another study has demonstrated that Staphylococcus aureus infection can induce the expression of the pro-inflammatory cytokine IL-1α." (PMID 40863173, 2025).
systemic inflammatory response syndrome (4 papers, 2010 to 2025). SIRS is a serious condition related to systemic inflammation, organ dysfunction, and organ failure. "In this regard, Tat-Tg mice were more susceptible to the systemic inflammatory response syndrome caused by the intra-peritoneal injection of LPS, based on the evidence of increased lethality and expression levels of TNF-α, IL-1α, IL-6 and CXCL10 in the peritoneal lavages of surviving animals." (PMID 26343909, 2015). "The Systemic Inflammatory Response Syndrome (SIRS) is triggered by endotoxin, which stimulates the release of inflammatory cytokines, such as TNF-α; IL-1α/β, and IL-17 into the circulation." (PMID 40821837, 2025).
ulcer (4 papers, 2013 to 2022). "In addition, patients who healed their ulcers had lower IL-1α at both the baseline and exit study visits." (PMID 24358275, 2013). "Patients who healed their ulcers also had lower serum CRP at visit 1 (p<0.05), lower interleukin-1 alpha (IL-1α) at visit 1 (p<0.05) and visit 4 (p<0.05), lower Granulocyte-Macrophage Colony-Stimulating Factor (GM-CSF) at visit 1 (p<0.05) and marginally lower GM-CSF at visit 4 (p=0.072)." (PMID 24358275, 2013).
abscess (3 papers, 2012 to 2024). An inflammatory process characterized by the accumulation of pus within a newly formed tissue cavity which is the result of a bacterial, fungal, or parasitic infection or the presence of a foreign body. "The failure in the generation of these pro-resolving macrophages drives the IL-1α-mediated cycle of inflammation with abscess-like accumulation of necrotic neutrophils." (PMID 38396021, 2024). "None of the other groups developed significant numbers of abscesses, again confirming the role of anti-IL-1α/β blockade in this outcome." (PMID 28358036, 2017).
acute coronary syndrome (3 papers, 2014 to 2022). Signs and symptoms related to acute ischemia of the myocardium secondary to coronary artery disease. "Infarcted cardiomyocytes cause the release of IL-1α, epithelial injury stimulates the release of IL-1β, while monocytes are a source of IL-1β in acute coronary syndromes." (PMID 35888173, 2022).
airway hyperresponsiveness (3 papers, 2019 to 2024). "We did this by stimulating airway fibroblasts with a 1 ng/ml dose of recombinant IL-1α, IL-1β or IL-33 for 24 hours and then assessed the release of inflammatory mediators known to be involved in chronic inflammation, and airway hyperresponsiveness in asthma." (PMID 32457454, 2020). "In both humans and mice, O3 causes damage to the airway epithelium, release of acute phase cytokines such as IL‐1α, recruitment of neutrophils and macrophages into the lungs, and airway hyperresponsiveness (AHR), a cardinal feature of asthma." (PMID 31544355, 2019). "Our data indicate that androgens augment pulmonary responses to ozone and that IL‐1α may contribute to the effects of androgens on ozone‐induced cellular inflammation but not airway hyperresponsiveness." (PMID 31544355, 2019). "Furthermore, an anti‐IL‐1α antibody reduced bronchoalveolar lavage neutrophils in intact males, although it did not alter ozone‐induced airway hyperresponsiveness." (PMID 31544355, 2019).
allergic asthma (3 papers, 2018 to 2023). A asthma with a basis in a pathological type I hypersensitivity reaction. "Pim-1 kinase inhibits the release of the proinflammatory factor IL-1α from airway epithelial cells in allergic asthma caused by house dust mites." (PMID 34547720, 2021). "IL-1α, IL-1β, and IL-1R1 are involved in several models of lung inflammation such as in allergic asthma induced by ovalbumin or cigarette smoke/viral exacerbation models." (PMID 29867931, 2018).
aneurysm (3 papers, 2018 to 2019). Bulging or ballooning in an area of an artery secondary to arterial wall weakening. "Patients with aneurysm have IL-1α levels directly correlated to the size of the overlying mural thrombus, and levels fall after repair, suggesting that thrombus may produce IL-1α in vivo." (PMID 30926232, 2019).
ankylosing spondylitis (3 papers, 2017 to 2020). An autoimmune chronic inflammatory disorder characterized by inflammation in the vertebral joints of the spine and sacroiliac joints. "Specifically, the rs2856836 variant and the rs17561 variant of the IL1A gene are associated with ankylosing spondylitis." (PMID 28081267, 2017). "For example, the 4-bp indel at rs3783553 and rs3783550 SNP at IL1A identified in this study have previously been reported to be associated with various cancers and severe inflammatory diseases, such as ankylosing spondylitis mostly in Asian populations, including Chinese Han52,53." (PMID 32066657, 2020). "There may be some false positive results, but it has been able to explain the trend of IL-1A and IL-1B in patients with ankylosing spondylitis." (PMID 28423679, 2017).
brain injury (3 papers, 2017 to 2023). Acute and chronic (see also brain INJURIES, CHRONIC) injuries to the brain, including the cerebral hemispheres, CEREBELLUM, and brain STEM. "Other experiments have provided evidence that CHI3L1, GPR68 and IL1A are involved in the response to traumatic brain injury." (PMID 28097054, 2017). "Elevated cytokines and other inflammatory mediators such as IL-1α, IL-6, and TNF-α were also confirmed in other studies of traumatic brain injury, in which the traumatic stress response was one of the causes." (PMID 39282512, 2023). "After ischemic brain injury, for example, combined blockade of both IL-1α and IL-1β is necessary for maximal protection, whereas neuroprotection after spinal cord injury is achieved by selective IL-1α, but not IL-1β, blockade." (PMID 29662944, 2018).
bronchiectasis (3 papers, 2012 to 2020). Segmental, irreversible dilation of the bronchial tree resulting in the accumulation of secretions which leads to obstruction. "Our results suggest relatively greater importance of the neutrophil-related mediators IL-8 and IL-1α, than IL-17A, in adult non-CF bronchiectasis airway mucosal pathophysiology." (PMID 25822228, 2015). "Compared to normal controls, subjects with non-CF bronchiectasis also had highly significantly elevated BALF levels of all measured Th17 pathway cytokines (IL-1α, IL1β, IL-6, IL-8, IL-23 and TNF-α (p<0.0001 for all)." (PMID 25822228, 2015). "The current data demonstrate highly significant increases in all Th17 pathway-associated chemokines and cytokines measured in the airways of adult bronchiectasis subjects, including pathway effectors (IL-17A, IL-6, IL-8 and TNF-α) and regulators (IL-1α, IL-1β, IL-6 and IL-23)." (PMID 25822228, 2015).
carotid atherosclerosis (3 papers, 2023 to 2024). A thickening and loss of elasticity of the walls of carotid arteries that occur with formation of atherosclerotic plaques. "IL1A allele 2 might influence the inflammatory environment in vascular endothelium and significantly increase the susceptibility of carotid atherosclerosis." (PMID 38827573, 2024). "Furthermore, multivariate logistic regression was employed to evaluate the risk of carotid atherosclerosis conferred by the high-risk interactive genotypes among IL1A rs1609682, HABP2 rs7923349, and ITGA2 rs1991013." (PMID 37292135, 2023). "In addition, prior studies also support the association between variant in IL1A gene and carotid atherosclerosis." (PMID 37292135, 2023). "Polymorphisms in IL1A can significantly increase the susceptibility for carotid atherosclerosis, and the IL1A allele 2 might influence the inflammatory environment in the vascular endothelium." (PMID 37292135, 2023). "In this study, we also revealed polymorphisms in IL1A were associated with carotid atherosclerosis." (PMID 37292135, 2023). "Multivariate logistic regression revealed that IL1A rs1609682 TT and HABP2 rs7923349 TT served as independent risk factors for carotid atherosclerosis (OR, 1.45, 95% CI: 1.034–2.032, p = 0.031, and OR, 1.829, 95% CI: 1.228–2.723, p = 0.003)." (PMID 37292135, 2023). "There was a significant gene–gene interaction observed in IL1A rs1609682, ITGA2 rs1991013, and HABP2 rs7923349, the high-risk interactive genotypes in the three variants served as independent risk factors of carotid atherosclerosis." (PMID 37292135, 2023). "The high-risk interactive genotypes among IL1A rs1609682, ITGA2 rs1991013, and HABP2 rs7923349 significantly increased the risk of carotid atherosclerosis." (PMID 37292135, 2023). "The results exhibited that the high-risk interactive genotypes in IL1A rs1609682, ITGA2 rs1991013, and HABP2 rs7923349 were independently associated with a higher risk for carotid atherosclerosis after adjusting covariates (OR, 2.08, 95% CI: 1.257–5.980, P < 0.001)." (PMID 37292135, 2023). "In addition, although we found that the high-risk interactions among IL1A rs1609682, ITGA2 rs1991013 and HABP2 rs7923349 increased the risk of carotid atherosclerosis, the detailed molecular mechanisms were not investigated." (PMID 37292135, 2023). "Univariate analyses revealed there were significant differences in genotype distribution of PPARA rs4253655, IL1A rs1609682, and HABP2 rs7923349 between subjects with and without carotid atherosclerosis (p < 0.05)." (PMID 38827573, 2024). "Moreover, univariate analyses showed that there were significant differences in genotype distributions of IL1A rs1609682, PPARA rs4253655, and HABP2 rs7923349 between individuals with and without carotid atherosclerosis (p < 0.05)." (PMID 37292135, 2023).
cervical squamous cell carcinoma (3 papers, 2014 to 2022). A squamous cell carcinoma arising from the cervical epithelium. "Real-time quantitative RT-PCR confirmed the elevated expression of IL-1α mRNA in cervical squamous cell carcinoma and adenocarcinoma tissue explants, compared with normal cervix." (PMID 25237386, 2014). "Notably, for histological type, CAMK2A, CYBB, IL1A, IL1B, and SLC25A5 were found to be upregulated in patients with cervical squamous cell carcinoma compared with those having cervical adenosquamous carcinoma (P < 0.05)." (PMID 36253777, 2022).
chronic gastritis (3 papers, 2013 to 2024). Inflammation of the stomach that is chronic in nature. "For instance, these exosomes modulate the expression of IL-1α in gastric epithelial cells, contributing to chronic gastritis." (PMID 39726601, 2024). "Analysis of exosomes from individuals with chronic gastritis infected with H. pylori showed upregulation of IL-1α and soluble IL-6 receptor (sIL-6R) in human gastric epithelial cells (GES-1)." (PMID 39726601, 2024). "Analysis of association of IL1A and IL1B gene polymorphisms in H. pylori-infected patients with chronic gastritis was performed separately for each gene." (PMID 23995914, 2013). "The present study examined the role of IL1A and IL1B polymorphisms and the co-existence of H. pylori infection in the susceptibility to the development of chronic gastritis in group of patients from Western Poland." (PMID 23995914, 2013). "Notably, levels of IL-1α, IL-1β, IL-6, and IL-12, which are the main contributors to human chronic gastritis, were decreased in Nrdc−/− mice." (PMID 28230087, 2017).
cognitive decline (3 papers, 2019 to 2025). "The authors concluded that microglial activation is a major causal factor, as its removal prevented cognitive decline and reduced a broad spectrum of cytokines (IL-1α, IL-1β, IL-3, IL-4, IL-5, GM-CSF)." (PMID 41155372, 2025). "Cognitive decline in episodic, semantic, and working memory was associated with higher IL-1α, IL-13, and MDC levels in the temporal cortex, respectively." (PMID 34218796, 2021).
dysplasia (3 papers, 2013 to 2023). A usually neoplastic transformation of the cell, associated with altered architectural tissue patterns. "The results of the present study did not reveal significant differences in salivary concentration of IL-1α, IL-6, IL-8, and TNF-α between patients with OPMDs without dysplasia and healthy individuals." (PMID 32245251, 2020).
enteritis (3 papers, 2017 to 2024). Inflammation of the small intestine. "Table highlighted the diagnostic importance of estimated pro-inflammatory cytokines and APPs, indicating their sensitivities as biomarkers for sheep enteritis, particularly emphasizing IL-1α, IL-6, TNF-α, and Hp due to their highest specificities, LRs, PPVs, and accuracy rates." (PMID 39394128, 2024). "The observation that IL-1α and IL-1β is reduced, while IL-1RA is kept high in M. capsulatus primed DC-T cell co-cultures is interesting in the light of M. capsulatus anti-inflammatory effects in a murine enteritis model." (PMID 28293233, 2017).
familial Mediterranean fever (3 papers, 2018 to 2025). Familial Mediterranean fever (FMF) is an autoinflammatory disorder characterized by recurrent short episodes of fever and serositis resulting in pain in the abdomen, chest, joints and muscles. "In familial Mediterranean fever (FMF), ex vivo LPS-stimulated PBMCs and monocytes produce more IL-1α and β, IL-6, IL-8, IL-12, IL-18, and TNFα, and in non-stimulated PBMCs higher production of IL-6 and TNFα was found, and also expression of CD11b was increased." (PMID 29515591, 2018).
Fever (3 papers, 2014 to 2023). Body temperature elevated above the normal range. "Intestinal dysbiosis has been associated with elevated levels of IL-1a and a response to infection generated by IL-1Ra causing fever, neutrophilia, and acute phase protein production." (PMID 38087374, 2023). "In conclusion, these data suggest that the evaluation of IL-1A, IL-1B and IL-18 gene SNPs can add useful information on the clinical course of patients affected by Mediterranean Spotted Fever, even if further confirmatory studies will be necessary." (PMID 36551320, 2022).
gastritis (3 papers, 2013 to 2022). Inflammation of the stomach. "IL1A and IL1B genes have been proposed as key factors in determining risk of gastritis and malignant transformation." (PMID 23995914, 2013). "Moreover, other inflammatory cytokines and chemokines (IL-27, IFN-β, IL-1α, IL-23, IL-22P70, TNF-α, IL-17A, IL-10, IL-1β, and MCP-1) were not showed dose-dependent changed in DFMO-treated mice compared to gastritis mice group." (PMID 32231118, 2020).
hemorrhage (3 papers, 2018 to 2025). Loss of blood from the vascular compartment to the exterior or into nonvascular body space as a result of rupture or severance of the blood vessels. "In a rat filament model of SAH, IL-1α was expressed mainly in microglia/macrophages after 12 h with higher expression in basal structures adjacent to hemorrhage site in addition to cortex, striatum, and hippocampus and colocalize with HO-1 in activated microglia." (PMID 30011792, 2018). "However, in a rat filament model of SAH, it was shown that heme upregulated the expression of HO-1 around the hemorrhage site and IL-1α, which was confirmed in-vitro by application of heme to organotypic slice cultures preferentially releasing IL-1α over IL-1β." (PMID 30011792, 2018). "The increase in serum levels of proinflammatory cytokines IL-1α, IL-1β, IL-6, and TNF-α in the groups submitted to hemorrhage agrees with findings in other studies showing greater production of these inflammatory mediators in renal injury." (PMID 29535870, 2018).
hidradenitis suppurativa (3 papers, 2020 to 2023). A chronic suppurative and cicatricial disease of the apocrine glands occurring chiefly in the axillae in women and in the groin and anal regions in men. "MABp1 is a human antibody targeting IL1A and is undergoing clinical trials for moderate to severe hidradenitis suppurativa patients not eligible for adalimumab." (PMID 32397371, 2020).
Hypoglycemia (3 papers, 2019 to 2024). A decreased concentration of glucose in the blood. "To support the involvement of IL-1 in modulation of hypoglycemia-induced counterregulatory responses, we showed that mice lacking both IL-1a and b (IL-1a/b KO) displayed less severe insulin-induced hypoglycemia than wild type controls." (PMID 30996341, 2019).
ileitis (3 papers, 2025). "In SAMP1/YitFc mice which spontaneously develop Crohn’s-like ileitis, administration of an anti-IL-1α antibody protects against inflammation and damage." (PMID 39935485, 2025).
incontinence (3 papers, 2021 to 2022). "In relation to measures of incontinence, the concentration of IL-1α was found to significantly increase with pad weight (P = 0.007), while IL-1 receptor antagonist concentration decreased as the average frequency of voids per day increased (P 0.039)." (PMID 33657181, 2021). "It has been proposed that IL-1α and TNF-α could serve as biomarkers of skin damage caused by urinary incontinence." (PMID 35053737, 2022).
keratitis (3 papers, 2011 to 2021). A corneal disease that is characterized by inflammation of the cornea. "The ocular response against infectious keratitis induces the secretion of several inflammatory cytokines, such as IL-1a, IL-1β, IL-6, IL-8, tumor necrosis factor α, and the infiltration of immune cells at the site of infection." (PMID 34436544, 2021). "Interestingly, the IL-1α response in the spleen was found to be dependent on interactions between AdV and integrins, and integrins have also been reported to be involved in AdV-induced keratitis." (PMID 22046344, 2011).
leishmaniasis (3 papers, 2013 to 2024). Infectious disease that is transmitted through the bite of hematophagous female phlebotomine sand flies. "Indeed, recent studies show that IL-1α activated by commensal bacteria in the skin amplifies the inflammatory response in leishmaniasis." (PMID 28192528, 2017). "In experimental leishmaniasis, mice lacking IL-1a or IL-1b displayed delayed disease development and more attenuated systemic inflammatory responses, while IL-1b has been associated with immunopathology in human CL caused by L. braziliensis." (PMID 38787268, 2024).
lung squamous cell carcinoma (3 papers, 2022 to 2025). "In the lung squamous cell carcinoma data set, the remaining genes, except IL1A and CCL20, also showed significant differences." (PMID 40016789, 2025).
lymph node metastasis (3 papers, 2007 to 2025). "The correlations between IL-1α expression and clinicopathological features (patient age, sex, site of presentation, differentiation, presence or absence of lymph node metastasis, and tumor size) were also investigated." (PMID 40940885, 2025). "Similarly for patients with lymph node metastasis we identified four proteins, namely IL1α, XIAP, STX2, and SHKBP1, whereas for patients with liver metastasis we identified IGF1, IL1α, IGFBP2, MAML3, and SHKBP1 as significant." (PMID 24282616, 2013).